SPAG5 (sperm associated antigen 5)
Diseases named in the same sentence as SPAG5 in open-access papers (continued):
Sharing a sentence is not in itself a finding about the gene and the disease.
ovarian carcinoma (continued). "However, the prognostic value of SPAG5 expression in ovarian cancer has rarely been studied." (PMID 31985007, 2020). "However, the role of SPAG5 in ovarian cancer has rarely been reported." (PMID 31985007, 2020). "Our results showed that SPAG5 could be used as a potential tumor marker for ovarian cancer." (PMID 31985007, 2020). "Multivariate analysis showed that SPAG5 expression (P = 0.001) and TNM staging (P = 0.002) were independent prognostic factors for the DFS of ovarian cancer." (PMID 31985007, 2020). "SPAG5 mRNA expression was significantly higher in ovarian cancer tissues than in matched noncancerous tissues." (PMID 31985007, 2020). "The high expression of SPAG5 in ovarian cancer was correlated with histological type (P = 0.009), lymph node metastasis (P = 0.001), distant metastasis (P = 0.001), TNM stage (P = 0.001), and prognosis (P = 0.001)." (PMID 31985007, 2020). "High SPAG5 expression (P = 0.001), tumor pathological grade (P = 0.022), lymph node metastasis (P = 0.001), distant metastasis (P = 0.001), and TNM stage (P = 0.001) were also correlated with the OS of the 102 ovarian cancer patients." (PMID 31985007, 2020). "Multivariate survival analysis showed that high SPAG5 expression and TNM staging could be used as individual prognostic factors for ovarian cancer." (PMID 31985007, 2020). "Univariate analysis revealed that high SPAG5 expression (P = 0.001), tumor pathological grade (P = 0.031), lymph node metastasis (P = 0.001), distant metastasis (P = 0.001), and TNM staging (P = 0.001) were correlated with DFS in the 102 patients with ovarian cancer." (PMID 31985007, 2020).
liver cancer (2 papers, 2021 to 2022). An epithelial or non-epithelial malignant neoplasm that arises from the liver. "The overexpression of SPAG5 promoted tumor growth and metastasis, as SPAG5 interacts with CEP55 to trigger the phosphorylation of AKT at Ser473, causing liver cancer." (PMID 34055888, 2021). "In liver cancer, hsa_circ_0074817| EBF1 targets miR-539-5p, targeting CDK4 and SPAG5." (PMID 34055888, 2021).
benign prostate hyperplasia (1 paper, 2016). "SPAG5 protein expression was increased in PCa tissues compared with the benign prostate hyperplasia, and the difference was significant." (PMID 27037000, 2016).
breast ductal carcinoma (1 paper, 2020). "Since SPAG5 and NuMA proteins play a significant role in the mitosis regulatory network and cell division, we aimed to study their mRNA levels as well as SPAG5 gene amplification correlated to clinicopathological status in ductal carcinoma of the breast." (PMID 32838814, 2020).
ciliopathies (1 paper, 2012). "In continuation with its expression pattern, this indicates that SPAG5 is a very likely candidate gene for (retinal) ciliopathies." (PMID 23351521, 2012). "This hypothesis is supported by the observed expression of Spag5 in tissues such as retina, kidney, brain and testis, which are often affected in ciliopathies." (PMID 23351521, 2012).
COVID-19 (1 paper, 2024). A disease caused by infection with severe acute respiratory syndrome coronavirus 2. "On the other hand, SPAG5 was found to be positively correlated with the immune cell infiltration of neoplastic lung tissue, suggesting its possible involvement in the regulation of the COVID-19-associated cytokine storm and subsequent lung injury." (PMID 39596028, 2024). "Among the analyzed core genes, only SPAG5 and TOP2A were characterized by a statistically significant up-regulation in critical COVID-19 stage compared to mild COVID-19 stage, which is in good agreement with published data." (PMID 39596028, 2024).
cystic kidney disease (1 paper, 2012). A congenital or acquired kidney disorder characterized by the presence of renal cysts. "Analyses indicated 13 genes, in addition to Nek8 and Ift20 within this area that could potentially result in cystic kidney disease, namely: RGD1309077Phf12, Flot2, Spag5, Sdf2, Supt6h, Proca1, Traf4, Sarm1, Nlk and Ksr1." (PMID 22899815, 2012).
endometrial carcinoma (1 paper, 2024). A malignant tumor arising from the epithelium that lines the cavity of the uterine body. "However, the role of SPAG5 in endometrial carcinoma (EC) is still unknown." (PMID 38862557, 2024).
estrogen-receptor negative breast cancer (1 paper, 2020). "SPAG5 might be an independent prognostic and predictive biomarker that may have clinical utility as a biomarker for combination cytotoxic chemotherapy sensitivity, especially in estrogen receptor-negative breast cancer." (PMID 31985007, 2020).
head and neck cancer (1 paper, 2016). A primary or metastatic malignant neoplasm affecting the head and neck. "In TCGA, the median SPAG5 expression in prostate, bladder, breast, and head and neck cancers (where normal tissues are available) is at least threefold over normal, suggesting that SPAG5 is a potentially valid CT antigen in those cancer types." (PMID 27549193, 2016).
leukaemia (1 paper, 2025). "The dynamic interaction between CDK1 and other key molecules, such as SPAG5, provides valuable targets for therapeutic intervention, aiming to disrupt the proliferative capacity of leukaemia cells and promote their elimination." (PMID 39762615, 2025). "These strategies aim to restore the normal function of SPAG5, inducing cell cycle arrest and apoptosis in leukaemia cells." (PMID 39762615, 2025).
multiple myeloma (1 paper, 2023). "In the context of multiple myeloma, the expression of the HNRNPA2B1, USP1, RRM1, SPAG5, PCNA and TOP2A genes has been studied." (PMID 37048102, 2023).
myeloma (1 paper, 2023). "SPAG5 gene expression correlates with myeloma cell malignancy, and SPAG5 overexpression is associated with poorer clinical outcomes." (PMID 37048102, 2023).
osteoarthritis (1 paper, 2022). A noninflammatory degenerative joint disease occurring chiefly in older persons, characterized by degeneration of the articular cartilage, hypertrophy of bone at the margins and changes in the synovial membrane. "Among them, SPAG5, CUX2, and THEMIS2 were identified as tissue-specific expressed hub genes, these 3 tissue-specific expressed hub genes have superior diagnostic value in the RA samples compared with osteoarthritis (OA) samples." (PMID 35368701, 2022).
ovarian tumors (1 paper, 2020). "The GSE26712 dataset also indicated that SPAG5 mRNA expression was significantly higher in ovarian tumors than that in normal ovarian cells (P < 0.001)." (PMID 31985007, 2020). "Similarly, in the GSE44104 dataset, SPAG5 mRNA expression was higher in malignant ovarian cancer than that in ovarian tumors with low malignant potential (LMP) (P < 0.001)." (PMID 31985007, 2020). "SPAG5 mRNA expression was lowest in wild-type (BRAF/KRAS/ERBB2) ovarian tumors, which differed from nonmutant tumors (P < 0.001) and wild-type (BRAF/KRAS) tumors (P < 0.001)." (PMID 31985007, 2020).
prostate adenocarcinoma (1 paper, 2016). "We also investigated SPAG5 expression in a clinical cohort that included 30 prostate adenocarcinoma and 7 NEPC patients." (PMID 27037000, 2016). "The RNA-seq data of this cohort showed that SPAG5 was significantly upregulated in NEPC samples compared with prostate adenocarcinoma samples." (PMID 27037000, 2016). "The results indicated that SPAG5 mRNA was upregulated in three NEPC models (LTL331R, LTL352, and LTL370) relative to these prostate adenocarcinoma models." (PMID 27037000, 2016). "In the current study, we identified that SPAG5 expression level is drastically increased in primary PCa relative to normal samples, metastatic PCa samples relative to primary PCa, CRPC relative to hormone naïve PCa, and NEPC relative to prostate adenocarcinoma, respectively." (PMID 27037000, 2016).
retinal ciliopathies (1 paper, 2012). "The association of SPAG5 with both USH2AisoB and NINLisoB and its localization in photoreceptor cells pinpoints SPAG5 as a functional candidate gene for retinal ciliopathies." (PMID 23351521, 2012).
cancer (30 papers, 2015 to 2025). A tumor composed of atypical neoplastic, often pleomorphic cells that invade other tissues. "The Sperm Associated antigen 5 (SPAG5) is a mitotic spindle associated protein with oncogenic function in several human cancers." (PMID 39164278, 2024). "Sperm-associated antigen 5 (SPAG5) is associated with tumour initiation, progression, and resistance to front-line therapeutics in many cancer types." (PMID 38610947, 2024). "At the gene-level, the cytolytic granzyme A (GZMA) and K (GZMK) enzyme, CD8A and the chemokine CXCL10 illustrious of T and NK-cells and the testis antigen SPAG5 were associated with infiltration to cancer tissue." (PMID 37391505, 2023). "Then SPAG5 (Sperm-associated antigen 5) is present, a novel oncogene in various cancers and highly expressed in BC, although its biological function and regulatory mechanism are unclear." (PMID 35456196, 2022). "For certain human cancers, sperm associated antigen 5 (SPAG5) exerts important functions for their development and progression." (PMID 34162370, 2021). "Overexpression of SPAG5 has been implicated in cancer growth and progression, and it is upregulated in breast cancer, lung cancer, bladder urothelial carcinoma and cervical cancer." (PMID 30249289, 2018). "Given its involvement in these pivotal interactions, SPAG5 could contribute to the prevention of genomic instability, which is a hallmark of cancer development, including AML." (PMID 39762615, 2025). "Additionally, the present study adds to the growing body of evidence that SPAG5 is associated with cancer progression and chemoresistance." (PMID 38610947, 2024). "Sperm-associated antigen 5 (SPAG5, also known as asstrin) is involved in mitotic spindle formation and chromosome segregation, and has carcinogenic effects in tumorigenesis of various cancer types." (PMID 35178291, 2022). "Sperm-associated antigen 5 (SPAG5) has been identified as a driver in several type of cancers." (PMID 35138218, 2022). "SPAG5 upregulation in several cancers has been associated with poor prognosis." (PMID 35559794, 2022). "It has been shown that patients with higher SPAG5 gene expression were at high risk of cancer." (PMID 32838814, 2020). "In addition, a previous study analyzed tumor-infiltrating immune cells in RNA-sequencing samples from TCGA and found that SPAG5 is a cancer/testis gene that is positively associated with CD8 T-cell infiltration." (PMID 30736840, 2019). "Furthermore, we revealed that high expression level of SPAG5 is closely associated with cancer phenotypes, including tumor size." (PMID 30249289, 2018). "Second, the effectiveness of cancer vaccine targets might be predicted via association with immune infiltration levels; based on our data, it appears that SPAG5 is a potential vaccine candidate for multiple cancers." (PMID 27549193, 2016). "Moreover, upregulation of SPAG5 is associated with poor prognosis in cancer patients." (PMID 35456552, 2022). "SPAG5, known for its role in spindle formation during cell division, has been identified as an oncogene in several cancers, although its specific impact on AML remains underexplored." (PMID 39762615, 2025). "As an oncogene, SPAG5 has received extension attention due to its overexpression in various cancers." (PMID 38807081, 2024). "Sperm-associated antigen 5 (SPAG5) regulates cancer cell invasion and is involved in the progression of many cancers." (PMID 38862557, 2024). "FeSiNTs-siSPAG5 efficiently down-regulated SPAG5 expression resulting in a decrease in cell proliferation and an increase of cancer cell apoptosis." (PMID 35456552, 2022). "Collectively, the results suggested that FeSiNTs/siSPAG5-mediated SPAG5 silencing had a marked anti-tumor effect by decreasing proliferation, and inducing cancer cell apoptosis and cell cycle arrest in vitro." (PMID 34162370, 2021). "Despite several reports of increased SPAG5 expression in cancer, the cellular and molecular events affected by this increase are still unclear." (PMID 32838814, 2020).
cancer (continued). "Increased SPAG5 mRNA expression in tumor tissues was reported in different cancers such as cervix, prostate, liver, lung, and bladder, indicating the higher SPAG5 levels the poorer prognosis and patient survival." (PMID 32838814, 2020). "Overexpression of SPAG5 in MDA-MB-231 cells increased the sphere-forming ability and the population of CD24-ESA+ cancer stem cells (CSCs), while SPAG5 knockdown had the opposite effects on Hs-578t cells." (PMID 30736840, 2019). "Recently, some studies reported that SPAG5 was amplified at the 17q11 region in some types of cancer and involved in various fundamental biological processes including cell proliferation." (PMID 30249289, 2018). "Our analyses on putative immunotherapy targets led to the findings on cancer vaccine candidate SPAG5 and dichotomized CD8 T-cell levels in tumors highly expressing inhibitory receptors." (PMID 27549193, 2016). "Targeting SPAG5 may represent a novel strategy to overcome barriers to current cancer therapies such as metastasis or recurrence after surgery and resistance to standard chemotherapy, endocrine therapy, and targeted therapies." (PMID 38610947, 2024). "Therefore, an in-depth understanding of the oncogenic role of SPAG5 is essential to uncover TNBC cancer pathology and develop novel therapeutic strategies." (PMID 38610947, 2024). "In vitro experiments showed that SPAG5 promotes cancer cell migration and invasion." (PMID 38862557, 2024). "In NSCLC, LINC01929 may promote cancer progression in part through sponging miR-1179 and this may then influence SPAG5." (PMID 35996496, 2022). "In NSCLC, miR-1179 suppresses cancer cell growth and invasion by direct targeting SPAG5." (PMID 36304306, 2022). "Consistently, SPAG5 was reported to promote cancer progression in a variety of cancers, and targeting of SPAG5 might be a potent strategy for cancer treatment." (PMID 35138218, 2022). "Recently, growing evidence has demonstrated that SPAG5 plays a role in cancers." (PMID 35138218, 2022). "SPAG5 promotes cell growth and progression in culture; therefore, we hypothesized that silencing of SPAG5 would affect the survival of cancer cells." (PMID 34162370, 2021). "Studies suggest that SPAG5 is involved in tumorigenesis and cancer progression." (PMID 34162370, 2021). "Aberrant SPAG5 expression has been reported in several cancer types." (PMID 33230261, 2021). "SPAG5 depletion strongly impaired cancer cell cycle progression, proliferation, and migration." (PMID 33230261, 2021). "Recently, SPAG5 has been suggested a novel oncogene in various cancers." (PMID 34162370, 2021). "Consequently, the present study aimed to use Fe-doped chrysotile nanotubes (FeSiNTs) to deliver an anti-cancer siRNA targeting the SPAG5 oncogene." (PMID 34162370, 2021). "SPAG5 was also proposed as a proliferative marker in early-stage of cancer." (PMID 32838814, 2020). "Notably, there is an established body of research in several types of cancer showing that SPAG5 is involved in tumorigenesis and patient prognosis." (PMID 30736840, 2019). "It was reported that SPAG5 is amplified at the 17q11 region in some types of cancer." (PMID 30249289, 2018). "Furthermore, our in vitro and in vivo data demonstrated that cancer cells with SPAG5 overexpression were more aggressive." (PMID 30089483, 2018). "In addition, the levels of SPAG5 protein in the cancer tissue samples and corresponding adjacent tissues were investigated by IHC with an anti-SPAG5 antibody." (PMID 30249289, 2018). "There has been accumulating evidence that shows that abnormally high expression of SPAG5 is closely related to cancer, and SPAG5 could serve as a novel cancer biomarker." (PMID 30249289, 2018). "Previous study reported overexpression of SPAG5 in several types of cancers." (PMID 27037000, 2016).
cancer (continued). "In addition, a comprehensive analysis of tumour immunity for cancer immunotherapy has also identified SPAG5 as a potential candidate for future vaccine development in multiple cancers, in which the median SPAG5 expression in these cancers is at least threefold over normal." (PMID 38610947, 2024). "Thus, SPAG5 could serve as a biomarker in predicting cancer proliferation, progression, and response to therapy and clinical outcomes." (PMID 38610947, 2024). "Targeting these SPAG5 regulators may be a potential therapeutic modality for cancer treatment." (PMID 38610947, 2024). "Furthermore, the upregulation of SPAG5 affected the response of cancer cells to chemotherapy." (PMID 30089483, 2018). "Future studies should also explore the relevance of SPAG5 in paediatric AML and its broader implications across other cancers." (PMID 39762615, 2025). "During mitosis, PLK1 interacts and phosphorylates the N-terminus of SPAG5 (also known as astrin), which has been reported to upregulate the PI3K/AKT pathway in cancer cells in vitro through the centrosome protein CEP55." (PMID 38534420, 2024). "Interestingly, SPAG5 overexpression was correlated with high levels of lymphocyte CD8+, macrophages, neutrophils, dendritic and B cells, positively associated with PD-1/PDL1, LAG3, GZMB and CTLA4 and SPAG5 antigens were suggested as valid immune stimulatory targets for anti-cancers therapy." (PMID 39164278, 2024). "Several other genes in our model have been independently verified as oncogenes (SPAG5, PARM1) or tumor suppressors (VEPH1, GLCE) in prostate or other cancers, showcasing the ability of our TET2-based model to capture these key changes." (PMID 33008340, 2020). "Besides the cell division-associated genes like CCNB2 and BUB1B, we also found genes such as TPX2, BIRC5, TOP2A, SPAG5 and HMGB1, were among the top 10 highly expressed genes in the cell subset, which were reported to be directly or indirectly associated with cancer invasion." (PMID 31888172, 2019). "Conversely, the positive interaction of SPAG5 with CDK1 may enhance cell cycle progression, potentially contributing to uncontrolled cell proliferation during cancer development." (PMID 39762615, 2025). "Although SPAG5 has pleiotropic roles in many cancer types, the function of SPAG5 in TNBC is not well defined and understood." (PMID 38610947, 2024). "We propose that expression of astrin-2 endows cancer cells with the ability to proliferate, despite a dysregulated coupling between mitochondrial metabolism and the cell cycle, making CLUH a possible novel therapeutic target in cancers overexpressing SPAG5." (PMID 35559794, 2022).